TET3 (tet methylcytosine dioxygenase 3)
Diseases named in the same sentence as TET3 in open-access papers (continued):
Sharing a sentence is not in itself a finding about the gene and the disease.
tumor (continued). "These compelling findings underscore the pivotal oncogenic role of TET3 across various tumor contexts and highlight the potential of TET3-targeted therapies as a promising avenue for effective cancer treatment." (PMID 39104395, 2024). "The results from molecular biology and cytology experiments validating the potential role of TET3 in tumor progression strengthen this argument." (PMID 39104395, 2024). "IscU2 depletion increased α-KG level and reduced tumor growth, and the IscU2 depletion-reduced tumor growth was largely alleviated by TET3 depletion." (PMID 37488138, 2023). "IHC analyses of DNA 5mC in tumor tissues showed that IscU2 depletion in the mice decreased the level of DNA 5mC, and this decrease was alleviated by TET3 depletion." (PMID 37488138, 2023). "It had been recently reported that TET3 was tightly related to the process of epigenetic modulation, embryonic development, stem cell renewal, and tumor." (PMID 36001230, 2023). "We found the TETl, TET2, and TET3 protein levels in tumor tissues were significantly lower than those in para cancerous tissues, and the decrease of TET1 has a positive correlation with the decrease of 5-hmC in tumor tissues." (PMID 37266610, 2023). "It has been confirmed that TET3 functions as a tumor promoter or tumor suppressor in different cancers and the different expression level of TET3 was associated with patients’ survival." (PMID 35757739, 2022). "With the exceptions of TET1 and TET3, the expression levels of the other 11 factors were significantly different in the tumor tissues and the adjacent mucosal tissues." (PMID 35281843, 2022). "By contrary, the tumor volume and weight in TET3-KD group were significantly decreased compared with those in the control group." (PMID 36518116, 2022). "The results revealed that the tumor volume and weight in TET3-OE group were significantly larger than those in the control group." (PMID 36518116, 2022). "All three erasers are notably related to the OS of GC patients despite the fact that only TET3 is significantly abnormally expressed in tumor samples." (PMID 36389669, 2022). "Although mutations of TET1 or TET3 are rarely detected in hematopoietic malignancies, in most TET2MT malignancies, TET1 and TET3 function as tumor repressors by compensating for TET2 activity." (PMID 36203205, 2022). "Data are conflicting regarding TET3 expression, with studies reporting both over- and underexpression in tumour tissue compared with normal mucosa." (PMID 32429269, 2020). "Tumour formation and expansion by the TET3 shRNA-treated GSCs were compared with that by control RNA-treated GSCs maintained under identical conditions." (PMID 26838672, 2016). "Together, these results indicate that knockdown of TET3 increases tumour progression and decreases the lifespan of GSC-grafted mice, in a manner opposite to knockdown of TLX." (PMID 26838672, 2016). "Stereological measurement of tumour volumes confirmed the development of significantly larger tumours in brains transplanted with GSCs treated with TET3 shRNA, compared with that in brains transplanted with control GSCs." (PMID 26838672, 2016). "Although growing evidence showing that epigenetic regulation plays an important role in cancer development, our knowledge on the role of TET family members, especially TET3, in tumour development is rather limited." (PMID 26838672, 2016). "In this study, we identified TET3 as a potential tumour suppressor that acts downstream of TLX to regulate GSC growth and self-renewal." (PMID 26838672, 2016). "The results of this study demonstrated that TLX is fundamental for maintaining GSC growth, self-renewal and in vivo tumour formation capacity, whereas TET3 is a potential tumour suppressor that inhibits GSC growth, self-renewal and tumorigenesis." (PMID 26838672, 2016).
tumor (continued). "Consequently, we assessed the expression of TET3 protein in four tumor cell lines (BGC-823, HepG2, A549, TPC-1) and their corresponding normal cell lines (GES-1, LX2, 16HBE, Nthy-ori-3-1)." (PMID 39104395, 2024). "Sunitinib, a selective multi-target tyrosine kinase inhibitor, was employed to assess whether TET3 affects tumor behavior via the RTK pathway." (PMID 39104395, 2024). "Notably, the analysis reveals that each TET family member, including TET3, displays unique expression patterns in at least ten detected tumor types." (PMID 39104395, 2024). "Interestingly, we found also that expression of TET3 is significantly higher in leukocytes from patients with grade G2 (moderately differentiated tumor) than G3 (poorly differentiated tumor) (p < 0.05)." (PMID 38499584, 2024). "Notably, TET3 was identified to promote cancer progression across various tumors, and its silencing was found to inhibit tumor malignancy and enhance chemotherapy sensitivity." (PMID 39104395, 2024). "Thus, we explored the potential involvement of TET3, which is expressed in the tumor models that we studied." (PMID 39388288, 2024). "However, TET1 and TET3 down-regulation sensitizes the breast tumor-initiating cells to paclitaxel and decreases the tumor growth and metastasis in vivo through down-regulation of the TNFα-p38-MAPK signaling pathway." (PMID 38203443, 2023). "However, there have been few studies on the effects of the TET3-AHR interaction on tumor lymphangiogenesis." (PMID 37718440, 2023). "Using WT and AHR−/− tumor cell models, we observed that TET3 could bind to AHR, and this binding can be disrupted by AHR-specific siRNA." (PMID 37718440, 2023). "Therefore, we detected the levels of 5-mC, 5-hmC, TETl, TET2, and TET3 in tumor tissues and the corresponding para cancerous tissues of 40 patients with HBV-related HCC." (PMID 37266610, 2023). "In these tumor spheres, the TET3 expression is increased and could be involved in the Programmed Cell Death 1 Ligand 1 (PD-L1) over-expression, an immune checkpoint ligand, by demethylation of its promoter." (PMID 38203443, 2023). "In the TET3-OE group, the ability of tumor cells to form spheroids was increased." (PMID 36518116, 2022). "Thus, it appears that the role of both TET1 and TET3 in hematological cancers (either oncogenic or tumor suppressive) is disease/context dependent and remains to be identified for MM." (PMID 36059621, 2022). "Furthermore, TET3 levels positively correlated with CDKN2B, ZIC2, and miR-196a levels, which appear to have anti-leukemic effects, thus suggesting a tumor suppressive role for TET3 in AML." (PMID 36059621, 2022). "In addition, in HNSCC tumor tissues, the expression level of the m5C eraser TET3 was significantly elevated, while that of TET2 was downregulated." (PMID 33912441, 2021). "In addition, the knockdown of TET3 essentially mimicked tumor hypoxia to effectuate the pro-EMT splicing switch of ESRP1 targets." (PMID 34362878, 2021). "According to multi-tumor data analysis, TET3 and TDG are highly expressed in most tumor types." (PMID 32637580, 2020). "Our data feed the ongoing debate regarding whether TET3 exerts an oncogenic role or a tumor suppressor role." (PMID 31611907, 2019). "TET1 enzyme, along with TET2 and TET3, contributes to DNA demethylation through its conversion of 5mC to 5hmC and is considered to be a tumour suppressor, acting to prevent cell proliferation and tumour metastasis in human solid tumours." (PMID 28587163, 2017). "TET3 mainly located in cytoplasm of both normal and tumor cells." (PMID 27141829, 2016). "Moreover, we identify TET3 as a potent tumour suppressor downstream of TLX to regulate the growth and self-renewal in GSCs." (PMID 26838672, 2016). "Additionally, animal experiments revealed that the herbicide glyphosate induces tumor development by triggering TET3-mediated DNA demethylation and it could leave long-lasting effects even after a removal of glyphosate." (PMID 40014756, 2025).
tumor (continued). "Notably, high expression of TET3 in ACC alone indicated a poor prognosis among tumor patients." (PMID 39104395, 2024). "Moreover, five writers (NOP2, NSUN2, NSUN3, NSUN4 and NSUN5), one reader (ALYREF) and two erasers (TET2 and TET3) were consistently upregulated in UCB tumor tissues compared to adjacent normal tissues from TCGA cohort (fold change > 1.1, P-value <0.05, occurrence rate > 50%)." (PMID 36806253, 2023). "Notably, we did not observe the direct association of TET3 with these factors, and found that several tumor suppressor genes (CDKN2B, ZIC2, and miR-196a) and oncogenes (PAX2, IL2RA, SOX11, and PAK7) were associated with TET3 in AML biology." (PMID 32209730, 2020). "Moreover, no tumor nodules were observed with subcutaneous injection of glyphosate/miR-182-5p/siRNA-TET3-exposed MCF10A, confirming that TET3 is implicated in glyphosate-mediated tumorigenic pathway." (PMID 31611907, 2019). "The results showed that knockdown of MYC or TET3 alone significantly attenuated TMEM65‐induced xenograft tumor growth, and the more pronounced inhibitory effects were observed following simultaneous knockdown of MYC and TET3." (PMID 40546127, 2025). "To avoid the potentially toxic effects of the combination administration of 10058‐F4 and Bobcat339 on mice, we stably knocked down MYC, TET3 alone or in combination in TMEM65‐overexpressing MDA‐231 cells and then carried out mouse xenograft tumor assays." (PMID 40546127, 2025). "The expression levels of three writers (DNMT1, DNMT3A, DNMT3B), two erasers (TET1, TET3), and eight readers (MBD4, ZBTB33, UHRF1, UHRF2, UNG, TDG, NTHL1, SMUG1) were dramatically higher in tumor tissues (p < 0.05)." (PMID 38317133, 2024). "Within the THCA patient subgroup, TET3 and AHR expression levels were significantly lower in the tumor normal subgroup compared to the tumor grade 1/2/3/4 subgroups." (PMID 37718440, 2023). "In erasers, TET1 and TET3 were highly expressed in tumor tissues, while TET2 was down-regulated in tumor tissues." (PMID 37907576, 2023). "Analysis of the TCGA database revealed higher expression levels of TET3 and AHR in tumor tissue compared to normal tissue in THCA." (PMID 37718440, 2023). "Previous studies reported that TET3 and AHR have multifunctional roles in tumor cell proliferation and invasion." (PMID 37718440, 2023). "In this study, the analysis of public databases, including TCGA, revealed higher expression levels of TET3 and AHR in tumor tissue compared to normal tissue in THCA." (PMID 37718440, 2023). "In TET2MT tumor cells, TET1 and TET3 partially compensate for TET2 activity and contribute to the pathogenesis of TET2MT hematopoietic malignancies." (PMID 36203205, 2022). "Several DNA5mC regulators were found to be significantly overexpressed in tumor tissues, including DNMT1, DNMT3B, TET2, TET3, MBD1, and SMUG1." (PMID 36425533, 2022). "Such tumor-promoting and repressive functions of TET1 and TET3 are most likely cancer type-specific." (PMID 36203205, 2022). "It is known from the literature that miR-767 drives tumorigenesis in other cancers via repression of the tumor suppressors TET1 and TET3, which are responsible for the transformation of 5-methylcytosines to 5-hydroxymethylcytosines (5hmC) in DNA." (PMID 34073664, 2021). "In contrast, data regarding TET3 expression are conflicting, with some authors showing down-regulation and others up-regulation in ESCC comparatively to non-tumour tissue." (PMID 32429269, 2020). "Tumor samples were classified as positive when the mRNA expression levels exceeded 0.580, 0.102, and 1.866 for TET1, TET2, and TET3, respectively." (PMID 31602281, 2019). "We generated methylation profiles of TET1, TET2 and TET3 genes in tumor samples obtained from 233 patients with HNSCC; these included 57 hypopharynx, 44 larynx, 69 oral cavity, and 63 oropharynx tumor samples." (PMID 29849955, 2018).
tumor (continued). "Compared with non-tumor tissues, TET2 and TET3 were significantly downregulated in ESCC tissues (P < 0.01), whereas TET1 expression showed no significant decrease in ESCC tissues." (PMID 27050164, 2016). "TET3 could upregulate IGF2BP3, an essential reader of m6A, leading to mRNA instability of a tumor suppressor gene NF1 and tumor progression in TNBC." (PMID 40014756, 2025). "Research has shown that TET1 is mainly expressed abnormally in solid tumours and can regulate the expression of oncogenes through DNA demethylation, while TET2 and TET3 play a role in regulating oncogenes and tumour suppressor genes in nonsolid tumours." (PMID 39823268, 2025). "In addition, this study found that the anticancer drug 5‐azacytidine (5‐AZA) prevents HCC tumor cell growth by inducing the expression of TET2 and TET3." (PMID 40599235, 2025). "uncovered that TET3 induced promoter hypomethylation of Mucin 13 boosted its expression in HCC cells and tumour stem cells, thereby enhancing the generation and activation of tumour stem cells characteristics." (PMID 39462685, 2024). "The role of TET2 in tumor resistance is not well studied, but the upregulation of TET3 has been shown to increase the expression of tumor suppressor genes, leading to the inhibition of growth and self-renewal ability in glioblastoma stem cells." (PMID 38067304, 2023). "Taken together, the overexpression of TET3 and AHR in THCA indicates their involvement in promoting tumor aggressiveness and targeting them could potentially serve as a treatment strategy for THCA." (PMID 37718440, 2023). "This study aimed to identify the levels of 5-hmC, 5-mC, TETl, TET2, TET3, IDH1, and IDH2 in tumor and the adjacent tissues, so as to explore whether the 5-hmC is decreased in HBV-related HCC tissues and, if possible, to explore the associated mechanism." (PMID 37266610, 2023). "Finally, Genistein, a bioactive isoflavone present mainly in soybean products, decreases the TET2 and TET3 expression and delays TNBC tumor growth in vivo." (PMID 38203443, 2023). "The tumour/normal TL ratio was significantly correlated with the 5-hmC level (high vs. low; P = 0.043) and frequency of low expression levels of TET1, TET2, and TET3 (0 vs. 1-3; P = 0.043)." (PMID 33758594, 2021). "Moreover, several tumor suppressors, including BTG2, TUSC1, BAK1, LATS2, FZD6 and PPP2R1B, were regarded as common targets of TET3." (PMID 32209730, 2020). "TET3 and TDG were significantly highly expressed in tumor tissues." (PMID 32637580, 2020). "In univariate analysis, tumor size, TNM stage and TET3 level were correlated with 5-year OS." (PMID 32014008, 2020). "We found that TET1 mRNA but not TET2 or TET3 was significantly reduced in tumor tissues compared with non-tumor tissues (P = 0.02, P = 0.55, and P = 0.21 respectively)." (PMID 31399111, 2019). "Furthermore, the roles of TET proteins in the regulation of cancer progression are probably different in that TET1 is primarily involved in tumor initiation while TET2 and TET3 are primarily involved in cancer metastasis." (PMID 27852070, 2017). "Based on the negative regulation of TET3 expression by TLX, we hypothesized that TET3 could function as a tumour suppressor to control GSC growth and self-renewal." (PMID 26838672, 2016). "Furthermore, we identified tumour suppressors, including BTG2, TUSC1, BAK1, LATS2, FZD6 and PPP2R1B, as common targets of TLX and TET3." (PMID 26838672, 2016). "There were comparable expression of TET2 and TET3 in both of HCC tumors and non-tumor tissues." (PMID 23671639, 2013). "Furthermore, TET3 can inhibit ovarian cancer because it blocks TGFβ1 (the most classical and frequently used EMT‐inducer)‐induced EMT through upregulation of miR‐30d, thus acting as a tumor suppressor." (PMID 40599235, 2025). "However, NSUN6, TET1, TET2, and TET3 did not have significant differences in tumor vs. normal tissues." (PMID 37907576, 2023).
tumor (continued). "Consistently, deletion of TET2, but not TET1 or TET3, also increases the size of tumor cells." (PMID 37550284, 2023). "Additionally, TET3 and AHR expression levels were lower in the tumor grade 1 subgroup compared to the tumor grade 2/3 subgroups and lower in the tumor grade 2 subgroup compared to the tumor grade 3 subgroup (P < 0.001)." (PMID 37718440, 2023). "Considering the high expression of DNMT3A, TET1, DNMT3B, TET3, UHRF2, DNMT1, UHRF1and TDG in Subtype B, changing the tumor microenvironment cell infiltration characteristics by reversing expression of these DNA methylation regulators may be more clinically practical." (PMID 35771147, 2022). "However, both tumor-promoting and tumor-repressive functions of TET1 and TET3 have been reported." (PMID 36203205, 2022). "Interestingly, we found that TET2 and TET3 were significantly higher in the tumor tissues compared with normal tissues, but not TET1." (PMID 29983831, 2018). "Furthermore, TET1 and TET3 expressions were decreased in tumor tissues from patients with intrahepatic tumor recurrence or extrahepatic metastasis compared with patients with no tumor recurrence (both P<0.05)." (PMID 28661477, 2017). "Our data applying qPCR, immunofluorescence, and Western blotting clearly show that TET2 and TET3 but not TET1 were significantly decreased in HCC tissue and different HCC cell lines compared to non-tumor liver tissues and hHeps." (PMID 26366235, 2015). "Comparative analysis of DIPG tumor tissue and non-neoplastic brain sections showed increased TET1 and TET3 mRNA expression in tumor relative to patient matched brain (as expressed in fold change)." (PMID 24894482, 2014). "These co-expression patterns based on primary tumor data are well-preserved in GSCs for TET2, but not for TET1 and TET3, strongly suggesting that TET2 is involved in regulating cell-cycle control and DNA damage repair, functions that have been previously linked to TET2 and 5hmC." (PMID 29587824, 2018). "TET2 and TET3 expression was also significantly decreased in tumor tissues compared with paired non-tumor tissues (TET2, P < 0.0001; TET3, P = 0.009), and the decrease in 5-hmC was significantly associated with the downregulation of TET2 expression (r = 0.405, P = 0.004)." (PMID 27050164, 2016). "Additionally, in an independent set of DIPG tumor samples, TET1 and TET3 mRNAs were found to be overexpressed relative to matched normal brain." (PMID 24894482, 2014).